TNF (tumor necrosis factor)
Diseases named in the same sentence as TNF in open-access papers (continued):
Sharing a sentence is not in itself a finding about the gene and the disease.
infection (continued). "Infection at early stage did not induce a significant change in cytokines production and IL-1β and TNF-α expression levels measured in hippocampal/thalamic were comparable to ME7 mice treated with saline." (PMID 35058740, 2021). "However, we found that similar to Tnf transcription, TNF release upon Mtb infection was partially dependent upon MYD88 and TLR2 and very modestly increased upon infection with PDIM- or ESX-1-mutant Mtb." (PMID 34755600, 2021). "TNFα pre‐treatment of HMVEC‐L did not lead to further increase in nucleocapsid protein‐positive cells compared to untreated HMVEC‐L after infection with 2 × 106 PFUs of SARS‐CoV‐2, despite increased ICAM‐1 intensity levels demonstrating TNFα‐driven HMVEC‐L cell activation." (PMID 34721846, 2021). "Interestingly, GO terms related to TNF signalling and production of IL6 were lost specifically following Erk1/2 inhibition during infection with wild type Nm, which correlated with the reduced infection rates by the wild type in absence of Erk1/2 signalling." (PMID 34863201, 2021). "Strong correlation between local concentration of TNF-α, IFN-ɣ, IL-8 and SwH1N1 load in the lung, as well as TNF-α, IL-8 and PRRSV lung titres suggested that local replication of both viruses also influenced the local cytokine response during infection." (PMID 33407470, 2021). "After polyclonal restimulation, frequencies of IFN-γ+TNF+IL-2+ triple-positive multifunctional CD4 T cells were enhanced in vaccinated C57BL/6 mice when compared to the unvaccinated C57BL/6 animals at weeks 2 and 6 post-infection." (PMID 34351501, 2021). "During infection, moDCs are recruited to the site of inflammation and matured upon TLR stimulation to prompt a pro-inflammatory cytokine/chemokine response, with the secretion of IL-6, MCP-1, and TNF-α." (PMID 33673203, 2021). "After infection, the population of GFP-negative cells comprising mainly uninfected cells and putative latently infected cells were sorted by FACS and subsequently stimulated with 5 ng/μl tumor necrosis factor alpha (TNF-α) and 350 μM vorinostat." (PMID 34872356, 2021). "Besides, W-KP2 infection significantly induced the up-regulation of pro-inflammatory cytokines, such as IL-1β, IL-6, TNF-α, and IFN-γ in mice at 72 h after infection." (PMID 33968007, 2021). "Therefore, cells from the adaptative immunity are fundamental to restrain infection in the tissues by producing inflammatory cytokines such as IFN-γ, TNF-α, and IL-17." (PMID 34869064, 2021). "Indeed, lethal infection with MRSA upregulated the production of IL-6, TNF-α, and MCP-1 in the circulation and organs such as the liver, lungs, and kidneys, which was correlated with the induction of CD38 associated with pro-inflammatory macrophages." (PMID 34681611, 2021). "TNF-α is expressed by both immune and non-immune cells, and its systemic expression is increased following infection by a variety of cardiotropic viruses including influenza, CVB, and HIV." (PMID 34696354, 2021). "We performed an infection with Gram‐positive bacteria L. monocytogenes at a multiplicity of infection of 10 in macrophages and found that the silencing of RNF10 showed a higher production of IL‐6 and TNF‐α after infection for 6 h." (PMID 33249776, 2021). "Macrophages and monocytes, recruited in response to the infection, release cytokines [interferons I/III (IFN-I/III)], but also proinflammatory Tumor Necrosis Factor alpha (TNF-α), Interleukin-1 (IL-1), IL-6 and IL-18 to prime adaptative T and B cell immune responses." (PMID 34335504, 2021). "Moreover, the IFN-γ and TNF responses to ESAT6/CFP10 in infants in Uganda increased with age, which would also support progressive exposure over time to or infection with M. tuberculosis or NTM." (PMID 33815390, 2021). "After infection, the levels of IL-6, IFN-γ and TNF-α on days 4 and 7 in the untreated group were significantly increased (P < 0.01), and treatment with loperamide and GOS could inhibit the secretion of IFN-γ and TNF-α." (PMID 33676495, 2021).
infection (continued). "It was also shown that the production of KC, IL-10, IL-6, TNF-α, and IL-1β was significantly enhanced when bacterial loads were also significantly increased after S. pneumoniae infection at 7 days after H9N2 virus (A/Duck/Hong Kong/702/1979) infection." (PMID 33722928, 2021). "LPS-stimulated PEC isolated at a later stage of infection were not able to produce inflammatory cytokines IL-6 and TNF-α." (PMID 33461599, 2021). "Baseline expression of TNF-α was increased in LTβR−/− mice but did not change significantly during the course of infection." (PMID 33753412, 2021). "On the other hand, induction of TNF upon infection was observed in Ctrl and LP 8% animals, but the same was not noticed in LP 3%-fed mice." (PMID 33815321, 2021). "Infection of host cells by virus can trigger an innate anti-viral inflammatory response, releasing a range of stimulatory cytokines like type I IFN, tumor necrosis factor (TNF), and IL-1, which can be crucial in triggering immune responses against TAAs." (PMID 34372501, 2021). "TNF (degree = 11), CXCL2 (degree = 8), CSF3 (degree = 5), HIST2H2BE (degree = 11) and FGF2 (degree = 10) family proteins were activated and had a strong interaction, indicating that cells had a strong inflammatory response after infection." (PMID 34632719, 2021). "In the early stages of infection, antigen-presenting cells (APCs) release IL-6 and IL-12, followed by the synthesis of IFN-α, IL-23, IL-1β, and IL-17 by lymphocytes, which further activate macrophages to produce TNF-α." (PMID 34679707, 2021). "We reported here that the serum levels of TNF-α, IL-6, IL-28B, IMA and PAPP-A changed during SARS-CoV-2 infection whereas cTnT and NT-proBNP were not significantly different between the early phase and the active phase of infection." (PMID 34884175, 2021). "p65 was present in nuclear fractions of uninfected cells following the addition of TNFα, which, when combined with the p50 data, indicates that NF-κB p50:p65 translocated into the nucleus in the absence of infection, but was nearly abolished in infected cells." (PMID 33857149, 2021). "In this case, EVs containing virus particles and exosomal proteins activate multiple molecules, initiate a productive infection of CD4+ T cells, and upregulate the expression of proinflammatory cytokines, such as interferon (IFN)-γ, tumor necrosis factor (TNF), interleukin (IL)-1β, and CCL5." (PMID 34988085, 2021). "The influence of the infection with S. Typhimurium and the absence of significant downregulation was observed in TNF-α." (PMID 33670419, 2021). "Loss of GO terms related to TNF signalling and production of IL6 following Erk1/2 inhibition during infection with wild type Nm correlated with the reduced infection of HIBCPP cells by the wild type in absence of Erk1/2 signalling." (PMID 34863201, 2021). "The peak of IL-13, IFNγ, and TNF levels in the BALF was at day 11 or earlier in adult mice infected with P. murina but not until day 28 post-infection in mice infected as pups (Figure A3A–C)." (PMID 34682248, 2021). "The increased release of TNF-α, IL-23, CCL2, CXCL8, and CXCL10 by sc1o-treated MdMs may contribute to a pro-inflammatory environment at the infection site and thereby promote the immune response against pathogens via several mechanisms." (PMID 33330947, 2021). "However, at 36 h post infection, high percentages of cell death were observed for the DENV2-infected (43.61%) and the TNF-α plus DENV2 (48.01%) treated cells." (PMID 34696472, 2021). "However, this Plasmodium-induced inflammatory response also controls parasite replication and resolves infection through IFN-γ and TNF mediated killing of parasite." (PMID 33746974, 2021). "Non-liver and non-infection-related correlates of TNFα identified in this study also feature in the extant literature." (PMID 34067023, 2021). "Moreover, the results showed that IFN1, TNF-α, MX1, and ISG15 were significantly decreased by the introduction of miR-15a-5p mimics upon SCRV infection." (PMID 33735323, 2021).
infection (continued). "The infection of murine in vitro generated Hoxb8 neutrophils with A. phagocytophilum induced the expression of inducible or type 2 nitric oxide synthase (iNOS or NOS2) mRNA and the secretion of significant amounts of MIP-1α (CCL3), RANTES (CCL5), and TNF." (PMID 33747981, 2021). "To test how the absence of TNF would affect C3 production during S. Tm infection, we infected TNFa−/− mice and heterozygous littermate controls with S. Tm." (PMID 34529751, 2021). "With the increased infection time, IL-1β and TNF levels did not consistently increase at 6 h postinfection compared to 3 h, whereas IL-6 and IL-10 did." (PMID 33664232, 2021). "We observed a complete lack of detectable TNF-α response from both monocytes and moDC following infection with live tachyzoites, as well an absent IL-12 response from moDC." (PMID 34576723, 2021). "In the early stages of the infection, a group of cytokines and pro-inflammatory chemokines are expressed including interleukin-1β (IL-1β), IL-2, IL-6, interleukin-8 (IL-8), both IFN-α/β, tumor necrosis factor (TNFα), CCL, CCL3, CCL5, CCL2, and IP-10." (PMID 34220861, 2021). "Frequencies of STM-specific IFN-γ, TNF-α and/or IL-17A-producing T cells measured in these tissues at 7 and 21 days post Salmoporc vaccination and/or STM infection were then compared between only vaccinated (VAC), vaccinated and infected (V+I), only infected (INF) and untreated control (CON) pigs." (PMID 34451970, 2021). "It has been shown that TNF–α expression levels increased significantly in sheep that were experimentally infected with BLV, and that this was responsible for virus elimination in the early infection stages." (PMID 33804456, 2021). "In addition to complement activation, lectins reduce therisk of infection by stimulating the secretion of interferongamma(IFN-γ), IL-17, IL-6, tumor necrosis factor-alpha(TNF-α) by macrophages." (PMID 35083404, 2021). "In vitro infection of human NK cells by A. fumigatus hyphae for 6 h increases the secretion of inflammatory cytokines, such as IFN-γ, TNF-α, and growth factor GM-CSF, as well as several chemokines, including CXCL8/IL-8, CCL3/MIP-1α, CCL4/MIP-1β, and XCL1/lymphotactin." (PMID 34575791, 2021). "For these assays, we monitored levels of TNFα, since the murine macrophages did not significantly produce IL-6 after infection with L. pneumophila." (PMID 34280250, 2021). "Additionally, there were fewer functional TNF-α+CD107a+IFN-γ+NK cells among TIGIT+NK cells and TIGIT−NK cells in HIV-1-infected individuals in the first, third and twelfth month of infection than healthy donors." (PMID 33717085, 2021). "Finally, both IFN-γ and TNF-α were considered relevant when induced by HBHA, both cytokines providing 100% specificity, and HBHA-induced IFN-γ allowed the detection of infection with a sensitivity of 80% (compared to 47% for TNF-α)." (PMID 33790886, 2021). "Moreover, infection with NTHi resulted in higher production of IL1β, IL6, and TNFα in Cyld−/− mice compared to WT mice." (PMID 33808506, 2021). "Thus, the initial control of infection requires the production of IL12, TNFα, and IFNγ by phagocytic cells." (PMID 34946140, 2021). "Analysis of relative expression over the 5 time points of infection revealed significant upregulation of TNFα, IL1β and IL2 at 28dpi, compared to the brain of non-infected PBS controls." (PMID 34899715, 2021). "PDGFRβ correlated negatively in BSIII–IV and positively in BSV–VI with several cytokines (IL-10, IL-12, IL-13, IL-2, IL-4 and TNF-α) but only in the absence of infection." (PMID 33723589, 2021). "Moreover, 24 h after infection, we detected the overexpression of IL-1β (precursor) and IL-1β (mature) proteins in cells treated with live bacteria at MOI 50 upwards and TNF-α protein overexpression exhibited at MOI 1 and above." (PMID 34831265, 2021).
infection (continued). "In addition, honey induces monocytes (MM6 cells) to secrete cytokines, tumor necrosis factor-α (TNF-α), interleukin-1 (IL-1), and interleukin-6 (IL-6), which activate the immune response to infection." (PMID 34443372, 2021). "It is tempting to speculate that patients who can produce less TNF-α and IFN-α have impaired mucosal immunity and are therefore more prone to develop infection-triggered ME/CFS." (PMID 35046929, 2021). "In contrast, an opposite scenario could be observed during the chronic stage of infection where Ly6Chi monocytes and DCs could be found in the brain of TKO mice which released higher levels of TNF and iNOS." (PMID 33968021, 2021). "Clinical indications in severe malaria were found to be linked with the blood stage of infection with an excessive release of inflammatory cytokines (TNF-α, IL-6, and INF-γ) which contribute to further severity of infection such as organ damage and severe anemia." (PMID 34975479, 2021). "The activity of IDO1 is irrelevant under basal conditions, but strongly inducible by several inflammatory stimuli, such as interferon-γ (IFN-γ), lipopolysaccharide (LPS), tumor necrosis factor α (TNF- α), proinflammatory interleukins (ILs), infection, and transforming growth factor β (TGF-β)." (PMID 34576041, 2021). "Moreover, the TNF-α mRNA expression level was lower (p < 0.01) in the lungs of group IV compared with the level in groups I, II, and III at day 5 post-infection." (PMID 34988139, 2021). "No significant induction of TNF-α was observed due to the infection with T. crassiceps in any group." (PMID 34684235, 2021). "Also, the network revealed the possible mechanisms of TNF and NCR3 in regulating T1DM, by anti-infection pathways and natural killer cell mediated immunity, respectively." (PMID 34311758, 2021). "In human macrophages, gene expression levels for IL‐1β, IL‐18, and TNF‐α from WT infections remained low and were never two‐fold higher than uninfected macrophages." (PMID 33970545, 2021). "Here, we show that infected STAB-1 KO mice produced reduced serum, liver and splenic levels of IL-6 and TNF-α as compared to WT mice, suggesting that STAB-1 participates in the regulation of the inflammatory cytokine response in Lm-targeted mouse organs upon infection." (PMID 34374322, 2021). "Interleukin-6 (IL-6) and tumor necrosis factor–α (TNF-α) were similarly induced during active infection, regardless of ICI treatment." (PMID 34407944, 2021). "Similar to WT MGAS315, single infections with either the Δrgg2 or Δrgg3 mutant resulted in undetectable TNF-α production (data not shown)." (PMID 33947757, 2021). "It is important to note that a study with murine microglial cells infected with T. gondii showed that TNF and NO production are crucial to control the infection even in the absence of IL-12 and IFN-γ." (PMID 35071042, 2021). "In contrast, administration of acetic acid, for which levels were also increased upon infection with A. fumigatus, did not play a protective role and increased the levels of the inflammatory cytokines IL-1β and TNF-α." (PMID 34445184, 2021). "The expression of IFN-γ, TNF-α, IL-15, and IL-17 secreted by pro-inflammatory Th1 and Th17 cells differed significantly between patients with and without this infection." (PMID 34026776, 2021). "In contrast, the frequencies of IFN-γ+ (6.0%) and TNF-α+ (6.2%) cells in the lung tissue of old RMs were higher than that in young RMs (3.3% and 3.3%, respectively; p < 0.0001), regardless of infection." (PMID 34471088, 2021). "MFI of the TNF-α and IL-6-producing LKS+ cells was higher in the spleen than in the bone marrow of the PCA2-infected mice, indicating that in response to the secondary infection the splenic HSPCs are better prepared to produce proinflammatory cytokines." (PMID 34975887, 2021).
infection (continued). "Importantly, lung tissue analysis in the diabetic mice showed a decreased number of macrophages, CD4+ T-cells, and lower expression of TNFα and IL-6 in the HFD group, compared to control DPP4H/M mice following infection." (PMID 33692997, 2021). "While TNFα secretion is a part of the hepatic acute phase response after TBI, IL-10 expression post-TBI impairs T-cell immunity, which decreases the ability to fight infection early after TBI." (PMID 34640381, 2021). "After single infection with H3N2, an elevated mRNA expression of pro-inflammatory cytokines TNF and IFN-γ (mean fold change of 2.22 and 1.86, respectively), and anti-inflammatory cytokines IL-10 and TGF-β (mean fold change of 1.92 and 2.40 respectively), was observed." (PMID 34858411, 2021). "Meanwhile, Exo-MSCs-M.tb obtained at 24, 96, and 120 hours post-infection failed to initiate the increase of TNF-α of macrophages." (PMID 33872217, 2021). "The development of specific T helper 1 (Th1) response, based on the production of proinflammatory cytokines, such as interferon-gamma (IFN-γ), interleukin 12 (IL-12), and tumor necrosis factor-alpha (TNF-α), can protect mammalian hosts from infection by the parasites." (PMID 33928168, 2021). "GSK872 also did not impact cell death and appeared to impact TNF and IL-1β expression for infections with PA14." (PMID 33664232, 2021). "The overexpression of circDtx1 could significantly inhibit the expression levels of interferon IFN1, inflammatory cytokines (TNF-α), and antiviral genes such as myxovirus resistance protein 1 (MX1) and ISG15 after SCRV infection." (PMID 33735323, 2021). "IL-1α, IL-1β, MIP-1α, and tumor necrosis factor alpha (TNF-α) were reduced in both IAV- and mock-infected animals at 24 h pbi during infection with each SGD mutant compared to their levels during infection with WT D39 (P < 0.05), except for D39ΔpurD in mock-infected animals (P > 0.05)." (PMID 33875471, 2021). "The animals were sacrificed 96 hours and 2 weeks after infection, their lungs removed, macerated and the leukocytes analyzed by flow cytometry for the intracellular expression of IDO, AhR, and cytokines (IL-12, TNF-α, IL-1β, IL-6, TGB-β, and IL-10) by CD11c+ myeloid cells." (PMID 33936043, 2021). "In adult Xenopus, FV3 infection also induces a rapid response (as early as 1dpi) of type I IFN and Mx1 and 2, as well as pro-inflammatory and inflammatory-related genes (IFNγ, IL-1β, and TNF-α) in the kidney." (PMID 34675918, 2021). "Furthermore, the ex-vivo infection model indicated SARS-CoV-2 attaches to human vascular endothelial cells in the presence of activation marker, TNF-α." (PMID 34161337, 2021). "In a transgenic mice model, it was demonstrated that CTLs collaborate during the acute phase of infection by releasing tumor necrosis factor α (TNF-α) and INF-γ without destruction of HBsAg positive hepatocytes." (PMID 34207116, 2021). "Tissue content of TNF-α was not altered, but other cytokines or proinflammatory modulators were increased at different times of infection, namely, IL-1β, MyD88, and RAGE." (PMID 34303703, 2021). "As expected, infection of macrophages with WT or Δrgg2 GAS grown in CDM resulted in macrophage stimulation, as indicated by activation of NF-κB and production of large amounts of tumor necrosis factor alpha (TNF-α) and interleukin 6 (IL-6)." (PMID 33947757, 2021). "Wild-type RVFV infection of human monocyte-derived macrophages can lead to a productive infection and inhibition of the innate immune response via decreased expression of IFN-α2, IFN-β, and TNF-α." (PMID 33923863, 2021). "Interestingly, Mmass infection significantly increased the TNF, IL-1β, and CXCL2 levels in BMDMs after 18 h of infection." (PMID 33473145, 2021). "In addition, the expression of IFN-γ, TNF-α, CD69, and IFN-γ mRNA in the lung CD4+ T cells and IFN-γ in spleen CD4+ T cells significantly elevated after infection in WT mice (p = 0.00012, 0.0172, 0.0038, 0.00562, and 0.0117, respectively)." (PMID 33628846, 2021).